TMEM161B-DT (TMEM161B divergent transcript)
Synonyms: uc.165; linc-POLR3G-8; TMEM161B-AS1
Gene: Long non-coding RNA gene on chromosome 5 (88,268,843 to 88,439,337, forward strand). Ensembl gene ENSG00000247828.
Gene Ontology:
Molecular function: structural constituent of ribosome
Cellular component: ribosome